ARHGAP25 (Rho GTPase activating protein 25)
Description:
GTPase activator for the Rho-type GTPases by converting them to an inactive GDP-bound state.
Synonyms: KIAA0053; HEL-S-308; KAIA0053
Tractability: PROTAC: ubiquitination databases record sites on it; its protein half-life has been measured.
Gene: Protein-coding gene on chromosome 2 (68,679,601 to 68,826,833, forward strand). Ensembl gene ENSG00000163219.
Subcellular location (Human Protein Atlas): Nucleoplasm; Vesicles
Pathways (Reactome):
Signal Transduction: RAC1 GTPase cycle
Gene Ontology:
Molecular function: GTPase activator activity
Biological process: actin filament organization; negative regulation of small GTPase mediated signal transduction; phagocytosis, engulfment; regulation of small GTPase mediated signal transduction; signal transduction
Cellular component: phagocytic cup; plasma membrane
Genetic constraint (gnomAD): Loss-of-function variants: 34 observed, 72.22 expected, observed/expected ratio (o/e) 0.47, 90% interval 0.36 to 0.63. The upper end of that interval is the gene's LOEUF score, 0.63, which puts it in group 2 of 6, group 1 being the genes least tolerant of losing a copy. Missense variants: 706 observed, 846.27 expected, observed/expected ratio (o/e) 0.83, 90% interval 0.78 to 0.89. Synonymous variants: 282 observed, 313.67 expected, observed/expected ratio (o/e) 0.9, 90% interval 0.81 to 0.99.
Homologues: Orthologues: chimpanzee ARHGAP25 (99% identical), macaque ARHGAP25 (98% identical), pig ARHGAP25 (89% identical), rabbit ARHGAP25 (89% identical), dog ARHGAP25 (88% identical), mouse Arhgap25 (87% identical), rat Arhgap25 (85% identical), guinea pig ARHGAP25 (77% identical), tropical clawed frog arhgap25 (52% identical), zebrafish arhgap25 (42% identical). Paralogues in human: ARHGAP22 (42% identical), ARHGAP24 (39% identical).
Diseases named in the same sentence as ARHGAP25 in open-access papers:
ARHGAP25 is named in the same sentence as 28 diseases in open-access papers, as found by Europe PMC text mining. Sharing a sentence is not in itself a finding about the gene and the disease. The quoted sentences say what the papers report.
lung cancer (6 papers, 2021 to 2025). A malignant neoplasm involving the lung. "In the study «Relationship between the expression of ARHGAP25 and RhoA in non−small cell lung cancer and vasculogenic mimicry» there were 130 patients." (PMID 40786517, 2025). "In lung cancer cells, a high ARHGAP25 level exhibits tumor suppressor activity and thus increases the overall survival of lung cancer patients." (PMID 39281318, 2024). "One study revealed that the abnormal expression of ARHGAP25 reduces lung cancer cell proliferation and migration." (PMID 36207695, 2022). "ARHGAP25 was mainly localized in the nucleus, and ARHGAP25 levels were decreased in lung cancer tissues (48.5%, 63/130) compared to paracancerous tissues (63.1%, 82/130)." (PMID 36207695, 2022). "Subsequently, cell colony formation and cell scratching assays showed that lung cancer cells produced a higher number of colonies and a remarkable increase in the number of migrated cells after ARHGAP25 expression was reduced." (PMID 36207695, 2022). "ARHGAP25 has also been shown to inhibit lung cancer cell development through Wnt/β-catenin signaling pathway." (PMID 33994864, 2021). "Consistently, ARHGAP25 has been shown to suppress lung cancer cell growth." (PMID 33994864, 2021). "Furthermore, they disclosed the tumor suppressive role of ARHGAP25 in lung cancer cell growth, migration, and invasion through Wnt/β-catenin signaling." (PMID 33994864, 2021). "ARHGAP25 has also been widely studied as a tumor suppressor gene in cancer, including Pancreatic adenocarcinoma (PAAD), NSCLC, Lung cancer, and CRC." (PMID 38041020, 2023).
osteosarcoma (5 papers, 2018 to 2023). A usually aggressive malignant bone-forming mesenchymal neoplasm, predominantly affecting adolescents and young adults. "However, analysis of osteosarcoma cells overexpressing the ARHGAP25 G218R‐mutant, combined with structural modeling, confirmed that the mutant protein had decreased GAP‐activity against Rac1, resulting in elevated Rac1 activity, increased cell spreading, and membrane ruffling." (PMID 34258505, 2021). "For this, we expressed the full‐length wild‐type ARHGAP25 and its mutant forms R193A (positive control) and G218R as GFP‐fusion proteins in U2OS osteosarcoma cells to test their GTPase activating effect by G‐LISA assay." (PMID 34258505, 2021). "However, whether ARHGAP25 can inhibit the metastasis of osteosarcoma has not been studied, and it can become the object of our subsequent research." (PMID 38041020, 2023).
alveolar rhabdomyosarcoma (4 papers, 2021 to 2023). A rapidly growing malignant mesenchymal neoplasm. "The invasion capability of alveolar rhabdomyosarcoma cells is controlled by the RhoE/ROCK/ARHGAP25 signaling pathway." (PMID 36207695, 2022). "The RhoE/ROCK/ARHGAP25 pathway was reported to control alveolar rhabdomyosarcoma cell invasion." (PMID 34856991, 2021). "ARHGAP25 has been found to suppress rhabdomyosarcoma cell invasion." (PMID 33994864, 2021). "provided the first evidence that ARHGAP25 regulates also non-hematopoietic cells by promoting the invasive potential of alveolar rhabdomyosarcoma cells through the regulation of RAC along the RHOE/ROCK/ARHGAP25/RAC axis." (PMID 37234175, 2023).
breast carcinoma (3 papers, 2021 to 2026). "Rho GTPase activating protein 25 (ARHGAP25) was the only ABP associated with a low metastatic potential of breast cancer cells." (PMID 39281318, 2024). "Also, in breast cancer tissues, ARHGAP25 is downregulated relative to normal tissues, and its knockdown in breast cancer cell lines decreased malignancy." (PMID 39281318, 2024). "Therefore, future studies are necessary to validate the prognostic value of ARHGAP25 in breast cancer." (PMID 39281318, 2024). "Thus, similar to ARHGAP25, its prognostic value for breast cancer patients is rather weak." (PMID 39281318, 2024).
Arthritis (2 papers, 2023 to 2025). Inflammation of a joint. "Our group previously demonstrated that the leukocyte-specific GTPase-activating protein ARHGAP25 regulates phagocyte effector functions and is crucial in the pathomechanism of autoantibody-induced arthritis." (PMID 40078992, 2025). "To investigate the role of ARHGAP25 in a complex, inflammatory process, we used the K/BxN serum transfer arthritis murine model." (PMID 37234175, 2023). "Our findings suggest that ARHGAP25 has a key role in the pathomechanism of autoantibody-induced arthritis in which it regulates inflammation via the I-κB/NF-κB/IL-1β axis with the involvement of both immune cells and fibroblast-like synoviocytes." (PMID 37234175, 2023). "Our present study proves that ARHGAP25 is a significant component of the development of autoantibody-induced arthritis." (PMID 37234175, 2023). "Taken together, our data indicate that ARHGAP25 is an important component of autoantibody-induced arthritis development, via the regulation of the cytokine environment." (PMID 37234175, 2023). "Here we investigate the role of ARHGAP25 in the complex inflammatory process of autoantibody-induced arthritis." (PMID 37234175, 2023). "Surprisingly, our recent study revealed that, besides leukocytes, ARHGAP25 is highly expressed in fibroblast-like synoviocytes and may be involved in their regulation during the development of serum-transfer arthritis." (PMID 40078992, 2025). "Since data are available only on the role of ARHGAP25 in neutrophilic granulocytes and B cells regarding immune cells, we investigated the role of ARHGAP25 in complex inflammatory conditions in the K/BxN serum transfer arthritis (STA) mouse model." (PMID 37234175, 2023). "Albeit the role of ARHGAP25 has been proven in regulating the functioning of phagocytes and osteoclasts, moreover, more and more studies are aiming to understand its role, as well as other GAPs in disease, little is known about their exact regulatory function in arthritis." (PMID 37234175, 2023). "However, similarly to the serum-transfer arthritis model, the absence of ARHGAP25 suppressed immune cell infiltration upon the second exposure of TNCB." (PMID 40078992, 2025). "Lacking ARHGAP25 significantly decreased the concentration of both cytokines compared to WT upon arthritis induction, which suggests that their lowered amount may lead to decreased phagocyte count and finally reduced cartilage destruction in the articular joint." (PMID 37234175, 2023).
colorectal cancer (2 papers, 2021 to 2022). A primary or metastatic malignant neoplasm that affects the colon or rectum. "Furthermore, researchers discovered that ARHGAP25 was downregulated in colorectal cancer (CRC) and that upregulating ARHGAP25 decreased CRC metastasis both in vivo and externally." (PMID 36207695, 2022). "In colorectal cancer, ARHGAP25 inhibits tumor metastasis via the Wnt/β-catenin pathway." (PMID 34856991, 2021). "Considering that ARHGAP25 could inhibit the Wnt pathway to limit colorectal cancer, we assumed that ARHGAP25 could also limit OS metastasis, therefore, resulting in a reasonable decrease of ARHGAP25 expression in OS metastasis." (PMID 34856991, 2021).
lymph node metastasis (2 papers, 2022 to 2025). "In a multivariate analysis, which included ARHGAP25, RhoA, lymph node metastasis (LNM), and TNM stage as covariates, the presence of VM increased the risk of death (multivariate HR 1.872, 95% CI: 1.195-2.933, p=0.006)." (PMID 40786517, 2025). "The expression levels of ARHGAP25 in NSCLC tissues were significantly associated with tumor size (P = 0.015), TNM stage (P = 0.013), and lymph node metastasis (LNM; P = 0.015), but not with other clinicopathological factors (P > 0.05)." (PMID 36207695, 2022).
non-small cell lung carcinoma (2 papers, 2022 to 2025). A group of at least three distinct histological types of lung cancer, including non-small cell squamous cell carcinoma, adenocarcinoma, and large cell carcinoma. "In this study, we examined the expression levels of ARHGAP25 and RhoA and the structure of VM in non-small cell lung cancer (NSCLC)." (PMID 36207695, 2022).
pancreatic adenocarcinoma (2 papers, 2021 to 2023). "The Rho GTPase-activating protein 25 (ARHGAP25) has been shown to specifically inactivate the Rho family GTPase Rac1, which plays an important role in pancreatic adenocarcinoma (PAAD) progression." (PMID 33994864, 2021).
pancreatic cancer (2 papers, 2021 to 2025). "Overexpression of ARHGAP25 inhibited cell growth of AsPC-1 human pancreatic cancer cells in vitro, while opposite results were observed in BxPC-3 human pancreatic cancer cells with ARHGAP25 knockdown." (PMID 33994864, 2021). "Furthermore, IHC staining revealed decreased ARHGAP25 expression levels in pancreatic tumor tissues compared with normal tissues (P=0.010)." (PMID 33994864, 2021). "However, the biological functions of ARHGAP25 in pancreatic cancer are poorly understood." (PMID 33994864, 2021). "Previous studies have demonstrated that Arhgap25 regulates the proliferation of human pancreatic cancer cells via HIF-1α, leading us to hypothesize that RhoA modulates glycolytic processes through Arhgap25/HIF-1α pathway." (PMID 40846818, 2025).
allergic contact dermatitis (1 paper, 2025). An inflammatory skin condition caused by an immune response to direct contact between the skin and an allergen. "Our data suggest that ARHGAP25 is involved in developing and causing allergic contact dermatitis by regulating leukocytes, mainly cytotoxic T cells and macrophages." (PMID 40078992, 2025). "Interestingly, examining skin samples of human patients suffering from allergic contact dermatitis also showed significantly increased expression of ARHGAP25 at the mRNA and protein levels." (PMID 40078992, 2025).
colon cancer (1 paper, 2021). "A putative molecular network study showed that ARHGAP25 and LCP2 targeted more than five DEGs to play more important roles in colon cancer metastasis." (PMID 34856991, 2021).
contact dermatitis (1 paper, 2025). An inflammatory skin condition caused by direct contact between the skin and either an irritating substance or an allergen. "ARHGAP25 expression increased in human patients suffering from contact dermatitis and in contact hypersensitivity induced in mice." (PMID 40078992, 2025).
lentivirus infection (1 paper, 2021). Virus diseases caused by the Lentivirus genus. "The BxPC-3 cell line, which has the highest ARHGAP25 expression, was selected to silence ARHGAP25 through lentivirus infection." (PMID 33994864, 2021).
migraine (1 paper, 2024). "However, the associations between SERPING1 and BRH (PP.H4.abf = 0.47), ARHGAP25 and VD (PP.H4.abf = 0.34), PLG and any migraine (PP.H4.abf = 0.30), as well as ISOC1 and VD (PP.H4.abf = 0.06), did not receive sufficient support from co‐localization analysis, with a PP.H4.abf value below 0.5." (PMID 38898596, 2024).
triple-negative breast carcinoma (1 paper, 2024). An invasive breast carcinoma which is negative for expression of estrogen receptor (ER), progesterone receptor (PR), and human epidermal growth factor receptor 2 (HER2). "All ABPs significantly correlating with the ability of the primary tumor to form distant metastases were preferentially expressed by HER2-positive and triple-negative breast cancer, even ARHGAP25 showing an inverse correlation with metastasis-free survival probability." (PMID 39281318, 2024).
tumor (15 papers, 2021 to 2025). "Univariate analysis suggested that the expression levels of ARHGAP25 and RhoA, VM, tumor size, TNM stage, and LNM were strongly linked with OS and DFS, which are critical factors influencing the future prognosis with NSCLC." (PMID 36207695, 2022). "Multivariate analysis confirmed that ARHGAP25, RhoA expression, VM, tumor size, TNM stage, and LNM were closely associated with OS and DFS and may be employed as independent prognostic markers of NSCLC." (PMID 36207695, 2022). "ARHGAP25 and RhoA expression is associated with VM and may be of potential value in predicting tumor metastasis, prognosis, and targeted therapy." (PMID 36207695, 2022). "The potential tumor-suppressing role of ARHGAP25 has recently been connected to various intracellular pathways." (PMID 39210013, 2024). "The outcomes revealed that the levels of CD37, GABRD and ARHGAP25 were significantly elevated in the tumor cells than that in the normal cell line." (PMID 37465666, 2023). "We should note that even though the expression of ARHGAP25 in tumor cells is infinitesimal compared to neutrophils (unpublished data), it still has a significant role in the regulation of tumor invasion and metastasis." (PMID 37234175, 2023). "Recent studies confirmed that in pathological conditions decreased expression of ARHGAP25 resulted in increased migration and metastasis of different tumor cell types." (PMID 37234175, 2023). "It will be interesting to examine the roles of ARHGAP22 and ARHGAP25 in invadopodia formation of tumor cells." (PMID 37482421, 2023). "At the same time, we used cytology-related experiments to explore the effect of ARHGAP25 on the migration ability of tumor cells." (PMID 36207695, 2022). "Other RhoGAPs, such as ARHGAP4, ARHGAP6, ARHGAP9, ARHGAP12 and ARHGAP25, have also demonstrated tumor suppressor roles in different types of tumors 26-30." (PMID 36168627, 2022). "We found that downregulated ARHGAP25 expression was significantly correlated with aggressive tumor characteristics, including tumor size (P=0.012) and T stage (P=0.036), but not with age, gender, tumor grade, and N stage." (PMID 33994864, 2021). "Consistently, the tumor weights and volumes in the ARHGAP25-OE group were significantly lower than those in the ARHGAP25-NC group, and vice versa in ARHGAP25 knockdown PAAD tumors." (PMID 33994864, 2021). "In conclusion, the present study revealed that ARHGAP25 acted as a tumor suppressor regulating cell growth and suppressed glycolysis through AKT/mTOR signaling in PAAD." (PMID 33994864, 2021). "The Rac GTPase-activating protein 25 (ARHGAP25) has been confirmed to act as a negative regulator of several tumor metastases." (PMID 34856991, 2021). "Consistently, in vivo tumorigenicity assays also confirmed that ARHGAP25 overexpression suppressed tumor growth." (PMID 33994864, 2021). "Rho GTPase-activating protein 25 (ARHGAP25) acts as a tumor suppressor by inhibiting the AKT/mTOR signaling pathway, and may provide a therapeutic target for PDAC." (PMID 40630951, 2025). "It was reported that gene expression of ARHGAP25 can be altered in different types of tumor cells." (PMID 40078992, 2025). "In addition, between tumor tissues and their paired adjacent normal tissues, ARHGAP25, SLAMF8 and OLR1 expression differed significantly." (PMID 38017548, 2023). "Based on transcriptome and IHC data, we hypothesized that ARHGAP25 might function as a tumor suppressor of PAAD." (PMID 33994864, 2021). "Altogether, these results conclude that ARHGAP25 acts as a tumor suppressor by inhibiting the AKT/mTOR signaling pathway, which might provide a therapeutic target for PAAD." (PMID 33994864, 2021). "ARHGAP25 positivity rates in NSCLC and paracancerous tumor-free tissues were 48.5% and 63.1%, respectively, whereas RhoA positivity rates were 62.3% and 18.5%, respectively." (PMID 36207695, 2022).
tumor (continued). "ARHGAP25 expression was found to be lower in NSCLC tissues (48.5%) than in nearby normal tissues (63.1%), and was correlated with larger tumor size (P = 0.015), LNM (P = 0.015), and later clinical stage (P = 0.013) in this study." (PMID 36207695, 2022). "Both Rho GTPase-activating protein 25 (ARHGAP25) and Ras homolog family member A (RhoA) are effective predictors of tumor metastasis." (PMID 36207695, 2022). "Meanwhile, more and more publications report ARHGAP25 as an essential regulator of migration and metastasis of tumor cells with non-hematopoietic origin." (PMID 40078992, 2025). "Although this protein was initially considered leukocyte-specific, its importance has also been described in many tumor cell types even though the expression level of ARHGAP25 in non-hematopoietic cells is usually very low." (PMID 40078992, 2025). "The role of ARHGAP25 might be particularly pronounced in MSI-high CRC, potentially leading to increased tumor invasiveness and metastatic capacity due to heightened mutation rates affecting cell motility." (PMID 39055563, 2024).
cancer (5 papers, 2021 to 2024). A tumor composed of atypical neoplastic, often pleomorphic cells that invade other tissues. "Contrary to its specific abundance in leukocytes, ARHGAP25’s involvement in various cancer types has emerged in recent years." (PMID 39210013, 2024). "Targeting ARHGAP25 expression has been shown to inhibit the growth and migration of other cancer cells." (PMID 34856991, 2021). "Upregulation of ARHGAP25 inhibited cancer cell growth in vivo and in vitro by suppressing glycolysis through inhibition of AKT/mTOR signaling pathway." (PMID 33994864, 2021). "Of course, ARHGAP25 may regulate different pathways in different tumors to play a role in cancer inhibition." (PMID 38041020, 2023). "Only a few studies reported the significance of ARHGAP25 in cancer." (PMID 33994864, 2021). "Mechanically, overexpression of ARHGAP25 inactivated AKT/mTOR signaling pathway by regulating Rac1/PAK1 signaling, which was in line with the results from the Gene set enrichment analysis on The Cancer Genome Atlas dataset." (PMID 33994864, 2021). "Even though the direct evidence of ARHGAP25 playing a relevant role in non-hematopoietic cells during pathophysiological processes is still insufficient, the possibility of it taking part in other pathways might open new avenues for cancer treatment." (PMID 39210013, 2024).
ARHGAP25 also shares sentences with these, for which no sentence is quoted: bone disorder (1 paper); gastric cancer (1); hepatocellular carcinoma (1); Insulin resistance (1); intracerebral hemorrhage (1); lung adenocarcinoma (1); lymphoma (1); melanoma (1); neuroblastoma (1); renal cell carcinoma (1).